CD4 (CD4 molecule)
Diseases named in the same sentence as CD4 in open-access papers (continued):
Sharing a sentence is not in itself a finding about the gene and the disease.
cancer (continued). "Although the exact mechanism of the altered proportions of CCR4+/CD3+ and central memory CD4+ cells in the gastric mucosa of patients with cancer is unknown, focusing on lymphocytes in the gastric mucosa might help improve our understanding of carcinogenesis after H. pylori eradication." (PMID 36569708, 2022). "In addition, some studies have shown that the reduction of immune infiltration in TME, especially CD4+ T cells and M1 macrophages, may lead to poor prognosis of cancer patients." (PMID 36606241, 2022). "Thus, harnessing endogenous CD4+ T cells to modulate the immune activity of the host immune system and activate the antitumor immune response is a promising strategy for the long-term control of cancer." (PMID 35874660, 2022). "Indeed, cytotoxic CD4+ T cells could directly contribute to the elimination of cancer cells that express MHC-II." (PMID 36139357, 2022). "On the one hand, neutrophils, B lymphocytes and some CD4+ T cells may stimulate cancer growth." (PMID 36741710, 2022). "In contrast, the existence and function of CD4 CTLs in cancer remain unclear." (PMID 35572552, 2022). "In addition, ablating TGF-βRII in CD4+ T cells dramatically halts cancer progression." (PMID 35720407, 2022). "Moreover, the role of CD4+ T cell depletion in cancer and other diseases is still poorly understood, and our data evidenced that a decrease in the exhaustion markers of circulating CD4 T lymphocytes seems relevant to improving the antitumoral function of CAR T cells." (PMID 35628256, 2022). "Thus, the frequency of CD4+ T cells with predominant T-bet expression may be a potential predictive biomarker for CpG ODN-based cancer immunotherapy." (PMID 35799134, 2022). "Additionally, TCOF1 expression level was significantly associated with infiltration levels of Cluster of Differentiation 8–positive (CD8+) T cells, CD4+ T cells, B cells, neutrophils, macrophages, and dendritic cells (DCs) in 14, 16, 12, 20, 13, and 17 cancer types, respectively." (PMID 35093935, 2022). "Furthermore, the administration of MCPyV viral-like proteins (VLPs) induced a strong immune response in mice, suggesting a good requisite for the development of preventive VLP-based cancer vaccines, since VLPs can trigger a strong CD4+ T-cell-mediated immune responses against oncoviruses." (PMID 36551547, 2022). "In cancers that CXCL13 harbor favorable prognosis, one study reported that CXCL13 was associated with better overall survival and positively correlated with infiltration of six immune cells (B cell, CD8+T cells, CD4+T cells, macrophages, neutrophils, dendritic cells) in SKCM." (PMID 35141160, 2022). "Indeed, preclinical analysis has shown FGFR inhibitors to broaden the T-cell repertoire in cancer models through increased CD4+ and CD8+ T-cell infiltration; the same analysis also demonstrated immune checkpoint inhibitors to focus this pre-existing T-cell response through clonal expansion." (PMID 36462464, 2022). "However, mTOR inhibitors may have both pro- and anti-inflammatory actions and prompt both initial stimulation of Type 1 T helper (Th1) CD4+ T cells as well as long-term expansion of Tregs in cancer." (PMID 36139669, 2022). "The levels of STAT5B positively associated with the infiltration of resting memory CD4+ T, resting mast, and naive B cells in most tumors; however, STAT5B negatively correlated with the infiltration of Tregs, gammadelta T cells, TFHs, activated NK cells, and memory B cells in different cancer types." (PMID 36176415, 2022). "In addition, there is a complicated interaction effect between IL-10 and the MAPK pathway, whereby the activation of the MAPK pathway, which increases the production of IL-10 and TGF by cancer cells by maturing immune suppressive regulatory CD4+ T-cells, results in a complex interaction effect." (PMID 36339551, 2022).
cancer (continued). "Thus, although excess mMDSCs and low CD4 T cells often occur together in cancer patients, our data suggest that different features of the immune profile in conjunction with the NDMI can be useful to describe variation in these two important immunological parameters." (PMID 36127421, 2022). "Furthermore, CD4+ T cells also play essential roles in cancer immunity." (PMID 35456701, 2022). "Notably, the results indicated that HNSC, KIRC, LGG, LIHC, PRAD, and THYM were six cancer types most strongly associated with KIF15 expression in immune cell infiltrating level, including B cells, CD8+ T cells, CD4+ T cells, macrophages, neutrophils, and dendritic cells." (PMID 35359374, 2022). "However, it should be noted that while an increase in ICOS expression in CD8+ T cells and non‐regulatory CD4+ T cells (non‐Tregs) is desirable for anti‐cancer immunity, higher ICOS expression in Tregs has been shown to be more immunosuppressive compared to lower ICOS expressing Tregs." (PMID 36176603, 2022). "CD4+ T cells can activate monocytes/macrophages, NK cells, and specific CD8+ cytotoxic T cells and are thus pivotal to the antitumor response, suggesting an explanation for the significant association between circulating CD4+ cells and OS previously demonstrated in some cancers." (PMID 36135052, 2022). "Since activated Treg cells may confer resistance to checkpoint inhibitors, the signaling pathway analysis of CD4+ T cells in TIL or in blood samples of cancer patients may enable an improved prediction and monitoring of response to checkpoint inhibitor therapy." (PMID 35158758, 2022). "Interestingly, M1 coinjection with cancer cells also resulted in decreased T-reg cell populations in CD4+ cells, which may have been related to IFNg-based macrophage activation and downstream M1–T cell crosstalk through IFNg/IL-12 signaling." (PMID 34835178, 2021). "In addition, NAT10 expression had significant correlations with infiltrating levels of B cells in 15 types of cancer, CD8+ T cells in 17 types of cancer, CD4+ T cells in 20 types of cancer, macrophages in 13 types of cancer, neutrophils in 23 types of cancer, and DCs in 19 types of cancer." (PMID 34094911, 2021). "Moreover, a shift from a Th1 to a Th2 cytokine response was observed in HSIL and cancer compared to normalcy and LSILs relatively, leading to suppressive mechanisms such as the immaturation of DC cells, differentiation of CD4+ T cells to Tregs and polarization of immunosuppressive macrophage." (PMID 33694292, 2021). "Moreover, a high CD4/CD8 ratio could be regarded as a marker of poor survival outcomes in cancer patients." (PMID 34957065, 2021). "Most steps in the cancer immunity cycle presented the highest activities in molecular phenotype C2, like cancer cell antigen release and presentation, priming and activation, recruitment of B cell, CD4 T cell, dendritic cell, eosinophil, macrophage, monocyte, T cell, Th17 cell, and Treg." (PMID 35178409, 2021). "Interestingly, the genes coding for chemokines such as CXCL1, CXCL2, CXCL3, and CXCL8 (IL-8) were strongly upregulated in CD4+ T cells co-cultured with cancer cells only, further suggesting the direct influence of cancer cells on chemokine expression in CD4+ T cells." (PMID 34439305, 2021). "Interestingly, the overexpression of angiogenesis and development of blood-vessel-related genes, such as VEGFs, in restimulated CD4+ T cells co-cultured with cancer cells compared to control CD4+ T cells restimulated alone indicated the cancer-specific induction of these genes." (PMID 34439305, 2021). "In different disease settings including cancer, certain subsets of CD4+ T cells have been reported to express FcγRIII, FcγRII, and/or FcγRI; the ligation of these receptors were reported to enhance interferon-gamma production and cytotoxicity in a subset of human CD4+ T-cells." (PMID 34447380, 2021).
cancer (continued). "The recent observation that CDK4/6 inhibitors, now widely employed to treat luminal-like BCs, not only restrain cancer cell proliferation but also favor antitumor immunity by inhibiting CD4+ Treg proliferation in preclinical models, may be important in this regard." (PMID 34552178, 2021). "In addition, whether the findings about TFs instructing the development of CD4+ CD8α+ IELs are generalizable to other tissue compartments or to cancer requires confirmation." (PMID 34910940, 2021). "In addition, the expression level of LPAR6 has significant correlations with infiltrating levels of CD8+ T cells in 24 types of cancer, CD4+ T cells in 26 types of cancer, neutrophils in 33 types of cancer, macrophages in 20 types of cancer and dendritic cells in 21 types of cancer." (PMID 34769557, 2021). "Notably, this study found that an early initiation of ART, before age 2 years, was associated with significantly lower odds of developing cancer, independent of CD4 lymphocyte nadir and WHO HIV clinical stage." (PMID 33803641, 2021). "Thus, employing CD4+ T cells and modifying their immunomodulatory properties have gained awareness, aiming to achieve higher immunotherapy response rates and long-term survival of cancer patients." (PMID 34335959, 2021). "Moreover, KIF18B expression correlated considerably positively with infiltrating levels of T cells CD4 memory activated in nine types of cancer, T cells follicular helper in 12 types of cancer, macrophages M0 in eight types of cancer, and macrophages M1 in nine types of cancer." (PMID 34109209, 2021). "Our results suggested that CD4+ GzmB+ T cells could be a potential target for cancer immunotherapy." (PMID 34631551, 2021). "High CD4+ TILs were associated with significantly better overall survival among oropharyngeal HNSCC (HR: 0.52; 95% CI: 0.31–0.89), as well as high CD8+ TILS in Human papillomavirus −ve and +ve cancers (HR: 0.39; 95% CI: 0.16–0.93 and HR: 0.40; 95% CI 0.21–0.76 respectively)." (PMID 33668519, 2021). "KIF18B expression also correlated markedly negatively with infiltrating levels of T cells CD4 memory resting in eight types of cancer, macrophages M2 in six types of cancer, dendritic cells resting in six types of cancer, and mast cells resting in eight types of cancer." (PMID 34109209, 2021). "OSBPL members exhibited the strongest positive correlations with the levels of CD4+ T cells, M1 macrophages, neutrophils, monocytes, and cancer-associated fibroblasts, while showing negative correlations with CD4+ T cells, type 2 helper T (Th2) cells, and monocytes by QuanTIseq." (PMID 34829830, 2021). "However, there is growing evidence supporting the role played by CD4+T cells in cancer immunology." (PMID 33842304, 2021). "Furthermore, like CD8+ T cells, CD4+ T cells can also act in a cytolytic fashion in human cancer." (PMID 34534438, 2021). "Here, we show that the CD4+ T cell exhaustion process induced by cancer cells may be reversible." (PMID 34439305, 2021). "However, transcriptomic analysis of DPBC vs DPHD CD4+ T cells indicated that the induction of a senescence program in CD4+ T cells might be different in cancer patients compared to HDs." (PMID 34386013, 2021). "We propose that the CD4-Nbs presented here could serve as versatile probes for stratifying patients and monitoring individual immune responses during personalized immunotherapy in both cancer and inflammatory diseases." (PMID 34956237, 2021). "In addition, JUN, a putative transforming and remodeling gene, high expression of these molecules in CD4+ TILs might contribute the cells epigenome vulnerable to immunoediting with the cancer development." (PMID 33301062, 2021). "In the high-risk group, the proportion of CD4+ T-cells memory resting was dramatically higher, possibly reducing the proliferation of CD8+ T cells, which prevented the organism’s immune system from recognizing the cancer cells and producing an effective immune response." (PMID 35127473, 2021).
cancer (continued). "However, is there any evidence that CD4+ T cells indeed play a relevant role in cancer patients?" (PMID 33546283, 2021). "The relationship between IGF2BP2 and 21 kinds of immune cells indicated a negative correlation between IGF2BP2 and B cells, CD4+ T cells, follicular helper T cells, regulatory T cells (Tregs), myeloid-derived suppressor cells, and cancer-associated fibroblast cells in HNSCC." (PMID 33816266, 2021). "In addition, Rap1b expression had significant correlation with infiltrating levels of B cells in 21 types of cancer, CD4 + T cells in 18 types of cancer, CD8 + T cells in 24 types of cancer, neutrophil in 27 types of cancer, macrophage in 26 types of cancer and dendritic in 26 types of cancer." (PMID 34346294, 2021). "We also find that the cancer-dependent CD4+ T cell exhaustion process may be reversible." (PMID 34439305, 2021). "Furthermore, the SRI expression was significantly correlated with the infiltration levels of B cells in 14 cancer types, CD8+T cells in 14 cancer types, CD4+T cells in 13 cancer types, the macrophages in 21 cancer types, the neutrophils in 16 cancer types, and the dendritic cells in 12 cancer types." (PMID 34869449, 2021). "CD4+ T cells are, on the other hand, activated through interaction with their antigen in the context of an HLA class II molecule, typically expressed by antigen-presenting cells (APCs), but also upregulated on cancer cells by IFN-γ stimulation and thus frequently expressed by immunogenic tumors." (PMID 34290704, 2021). "The higher H3 density in CD4+ T cells was consistent with low expression of PD-L1 compared to CD4+ T cells exposed to cancer cells, which were characterized by decreased compaction of chromatin and shifted H3K27me3, highlighting the alteration of the chromatin status in CD4+ T cells upon exhaustion." (PMID 34439305, 2021). "Immune escaping is a common feature of carcinomas and is achieved by multiple mechanisms, one of which is the negative modulation of CD4+ and CD8+ T effector (Teff) lymphocytes, caused by the activity of forkhead box protein 3 (FOXP3)-positive T regulatory cells (Treg)." (PMID 34539667, 2021). "Alternatively, there is evidence that CD4 count decline could be due to undiagnosed cancer, rather than causing cancer." (PMID 33094910, 2020). "Interestingly, elevated sCD40L levels in cancer patients as a result of platelet activation have been suggested to play an immunosuppressive role in part by upregulation the expression of PD-1 receptors on CD4+ T cells." (PMID 32695883, 2020). "Moreover, DEPTH scores were inversely correlated with the ratios of immune-stimulatory signature (CD8+ T cells) to immune-inhibitory signature (CD4+ regulatory T cells) in pan-cancer (p = 5.14 × 10−181, ρ = −0.31) and in 12 individual cancer types (FDRsp < 0.05)." (PMID 32917965, 2020). "We evaluated whether the cytokine environment, even at advanced stages of cancer, could influence the percentages of CD4+ T-lymphocyte subpopulations, in particular Th1 (CD4+ T-bet+), Th2 (CD4+ CRTH2+), Th17 (CD4+ RORγ+ cells), and Treg (CD4+CD25+CD127-) subpopulations." (PMID 33167343, 2020). "In effector cells harvested from ascites of patients suffering from EpCAM-positive cancers, the bAb has further been shown to induce effector cytokines such as interferon-γ and upregulation of surface-expressed CD107a indicative of cytotoxic granule release in both CD4+ and CD8+ T cells." (PMID 32438548, 2020). "On the other hand, CD4+ Th2 cells, CD4+ T regulatory (TReg) cells, type 2 NK T cells, myeloid-derived suppressor cells, immature DCs, and M2 macrophages could suppress antitumor immunity and promote cancer progression." (PMID 32398657, 2020). "However, contradictory theories exist regarding the role of CD4+ T cells in cancer." (PMID 33584797, 2020).
cancer (continued). "The increased proportion of activated cervical T cells associated with HPV and HIV infection, as well as HPV-associated lesions, together with the HIV-induced depletion of cervical CD4 T cells, may increase the risk for HPV infection, associated premalignant lesions and cancer in HIV+ women." (PMID 33007050, 2020). "However, it may have been a major confounding factor in previous studies showing conflicting correlations with prognosis for CD4+FOXP3+ T cells in cancer." (PMID 32377339, 2020). "In this study, using 13 TCGA cancer datasets, we aimed to portray major molecular cancer subtypes by overlaying MHC expression clusters together with expression of immunoinhibitors and CAGs, frequencies of nonsynonymous mutations, and levels of T CD4 and T CD8." (PMID 33282963, 2020). "Since HLA-DR mediated antigen presentation is critical for priming CD4+ T cell effector functions, HLA-DR can also be considered to be an integral, upstream part of this anti-carcinoma, TH1 axis, suggesting that future studies may benefit from inclusion of HLA-DR into prognostic scoring panels." (PMID 32306077, 2020). "Therefore, we hypothesized that SMG would disrupt the mechanism of immune evasion in E.G7 cancer cells and lead to increased responses of CD4+ T cells." (PMID 31602007, 2019). "The function of MDSCs in cancer is inhibiting T cell function, that exacerbate cancer, but MDSCs might alleviate ischemic injury by suppression of detrimental responses of γδ T cells, CD4+ T cells, and CD8+ T cells, which contribute to ischemic injury." (PMID 31048856, 2019). "CD4+ T cells recognize cancer antigens, and activated M1 macrophages may inhibit cancer growth." (PMID 32117786, 2019). "In addition, LAYN expression has significant correlations with infiltrating levels of CD8+ T cells in 18 types of cancer, CD4+ T cells in 23 types of cancer, macrophages in 23 types of cancer, neutrophils in 19 types of cancer, and dendritic cells in 25 types of cancer." (PMID 30761122, 2019). "Importantly, as in mice, split tolerance selectively involving CD4+ T cells is a primary mechanism limiting cancer vaccine efficacy in humans that may be exploited to safely elicit antitumor immunity." (PMID 31010434, 2019). "Therefore, we investigated whether naturally occurring TCR from 19305DP without affinity enhancement could transfer high-avidity recognition of cancer cells to donor CD4+ T cells in addition to CD8+ T cells by retroviral TCR gene-engineering." (PMID 30626427, 2019). "Moreover, developing new strategies aimed at generating optimal CD4+ T cell responses and memory in the context of chronic antigen exposure may offer treatments for cancers that are resistant to current immunotherapies." (PMID 31379821, 2019). "This same patient population also expresses higher levels of PD-1 on their CD4+ T cells when compared to those of healthy controls and this is associated with T cell exhaustion; further, similar to CTLA-4, PD-1 levels are also related to HIV viral load and cancer progression." (PMID 31113482, 2019). "However, the role of CD4+ TRM cells in immunity to cancer remains undefined." (PMID 31230406, 2019). "The low levels of CD4+ T cells could decrease cancer immunosurveillance." (PMID 31305456, 2019). "Furthermore, therapeutic agents have been described to influence the Treg-population: in cancer patients IL-2 increases the amount of Tregs and prostaglandin E2 can be used to induce Foxp3-expression and to increase suppressive activity of CD4 + CD25 + cells." (PMID 29032503, 2018). "This could be because, in the early ART era, therapy was initiated at a lower nadir CD4 cell count, at which full restoration of cervical mucosal immunity was not obtained while life expectancy of patients and their likelihood to develop cancers were higher." (PMID 29107561, 2018).